HAUS8 (HAUS augmin like complex subunit 8)
Description:
Contributes to mitotic spindle assembly, maintenance of centrosome integrity and completion of cytokinesis as part of the HAUS augmin-like complex.
Synonyms: HICE1; MGC20533; NY-SAR-48; DGT4
Tractability: PROTAC: ubiquitination databases record sites on it; its protein half-life has been measured.
Gene: Protein-coding gene on chromosome 19 (17,049,729 to 17,075,625, reverse strand). Ensembl gene ENSG00000131351.
Subcellular location: Cytoplasm; Cytoplasm, cytoskeleton, microtubule organizing center, centrosome; Cytoplasm, cytoskeleton, spindle; Cytoplasm, cytoskeleton, spindle pole
Pathways (Reactome):
Cell Cycle: AURKA Activation by TPX2; Loss of Nlp from mitotic centrosomes; Loss of proteins required for interphase microtubule organization from the centrosome; Recruitment of NuMA to mitotic centrosomes; Recruitment of mitotic centrosome proteins and complexes; Regulation of PLK1 Activity at G2/M Transition
Organelle biogenesis and maintenance: Anchoring of the basal body to the plasma membrane
Gene Ontology:
Molecular function: protein binding
Biological process: centrosome cycle; spindle assembly; regulation of microtubule nucleation
Cellular component: centrosome; HAUS complex; mitotic spindle microtubule; cytosol; cytoplasm; spindle; spindle pole
Genetic constraint (gnomAD): Loss-of-function variants: 35 observed, 40.7 expected, observed/expected ratio (o/e) 0.86, 90% interval 0.66 to 1.14. The upper end of that interval is the gene's LOEUF score, 1.14, which puts it in group 5 of 6, group 1 being the genes least tolerant of losing a copy. Missense variants: 479 observed, 514.81 expected, observed/expected ratio (o/e) 0.93, 90% interval 0.86 to 1. Synonymous variants: 196 observed, 210.75 expected, observed/expected ratio (o/e) 0.93, 90% interval 0.83 to 1.05.
Homologues: Orthologues: chimpanzee HAUS8 (97% identical), macaque HAUS8 (90% identical), pig HAUS8 (68% identical), dog HAUS8 (66% identical), guinea pig HAUS8 (54% identical), rat Haus8 (49% identical), mouse Haus8 (48% identical), tropical clawed frog haus8 (32% identical), zebrafish haus8 (24% identical).
Diseases named in the same sentence as HAUS8 in open-access papers:
HAUS8 is named in the same sentence as 5 diseases in open-access papers, as found by Europe PMC text mining. Sharing a sentence is not in itself a finding about the gene and the disease. The quoted sentences say what the papers report.
glioma (1 paper, 2023). A benign or malignant brain and spinal cord tumor that arises from glial cells (astrocytes, oligodendrocytes, ependymal cells). "Low expression of HAUS4 and HAUS6 and high expression of HAUS1, HAUS3, HAUS5, HAUS7, HAUS8 may be risk factors for poor prognosis in glioma patients." (PMID 37161065, 2023). "The research found that expression levels of the Augmin family genes HAUS1, HAUS3, HAUS4, HAUS5, HAUS6, HAUS7, and HAUS8 was all related with survival rates of glioma patients." (PMID 37161065, 2023).
viral infection (1 paper, 2020). "Among the 10 upregulated genes, several are involved in immune signaling of the viral infection, such as SMAD4, ATP binding cassette, HAUS8, FCH domain, ubiquitin peptidase 20, and heteronuclear Ribonuclear Protein C (hnRNP C)." (PMID 32526950, 2020).
cancer (2 papers, 2022). A tumor composed of atypical neoplastic, often pleomorphic cells that invade other tissues. "Some genes always selected by each method were found (COPS7B, DONSON, GTF2E2, HAUS8, PRH2, and ZNF18) with known roles in cancer formation and progression." (PMID 35954157, 2022).
HAUS8 also shares sentences with these, for which no sentence is quoted: Renal Cell Cancer (1 paper); tumor (1).